COA3 (cytochrome c oxidase assembly factor 3)
Description:
Core component of the MITRAC (mitochondrial translation regulation assembly intermediate of cytochrome c oxidase complex) complex, that regulates cytochrome c oxidase assembly. MITRAC complexes regulate both translation of mitochondrial encoded components and assembly of nuclear-encoded components imported in mitochondrion. Required for efficient translation of MT-CO1 and mitochondrial respiratory chain complex IV assembly.
Synonyms: CCDC56; MITRAC12; HSPC009; COX25; hCOA3; MC4DN14
Tractability: Antibody: UniProt predicts a signal peptide or a membrane-spanning region. PROTAC: ubiquitination databases record sites on it; its protein half-life has been measured.
Gene: Protein-coding gene on chromosome 17 (42,795,147 to 42,798,704, reverse strand). Ensembl gene ENSG00000183978.
Subcellular location: Mitochondrion inner membrane
Subcellular location (Human Protein Atlas): Mitochondria
Pathways (Reactome):
Metabolism: Complex IV assembly
Gene Ontology:
Molecular function: protein binding; protein folding chaperone
Biological process: mitochondrial respiratory chain complex IV assembly; positive regulation of mitochondrial translation; protein folding
Cellular component: mitochondrial inner membrane; mitochondrion
Genetic constraint (gnomAD): Loss-of-function variants: 11 observed, 10.45 expected, observed/expected ratio (o/e) 1.05, 90% interval 0.66 to 1.69. The upper end of that interval is the gene's LOEUF score, 1.69, which puts it in group 6 of 6, group 1 being the genes least tolerant of losing a copy. Missense variants: 141 observed, 149.09 expected, observed/expected ratio (o/e) 0.95, 90% interval 0.82 to 1.09. Synonymous variants: 57 observed, 67.59 expected, observed/expected ratio (o/e) 0.84, 90% interval 0.68 to 1.05.
Gene-disease validity (ClinGen):
ClinGen rates the evidence that COA3 causes each of these diseases.
mitochondrial disease (autosomal recessive): Limited.
Homologues: Orthologues: chimpanzee COA3 (100% identical), macaque CCDC56 (92% identical), dog CCDC56 (85% identical), pig COA3 (85% identical), rat Coa3 (84% identical), mouse Coa3 (82% identical), rabbit COA3 (82% identical), guinea pig COA3 (80% identical), tropical clawed frog coa3 (57% identical), zebrafish coa3a (49% identical), Caenorhabditis elegans coa-3 (25% identical).
Diseases named in the same sentence as COA3 in open-access papers:
COA3 is named in the same sentence as 9 diseases in open-access papers, as found by Europe PMC text mining. Sharing a sentence is not in itself a finding about the gene and the disease. The quoted sentences say what the papers report.
motor neuron degeneration (1 paper, 2025). "SLC25A20 and FDX1 emphasized mitochondrial lipid biosynthesis and catabolism, while COA3 linked to mitochondrial genetic information processing and protein translation, suggesting broader biogenesis defects in motor neuron degeneration." (PMID 40864790, 2025).
neuroblastoma (1 paper, 2022). Neuroblastoma (NB) is the most common solid, extracranial childhood tumor. "We probed COA3, COA6, and COA129 neuroblastoma PDX cells with anti-human CD111, CD112, syndecan, and HVEM and found that each PDX expressed all four viral receptors." (PMID 35159029, 2022).
sarcoma (1 paper, 2022). A usually aggressive malignant neoplasm of the soft tissue or bone. "Such quantities of mIL-12 from the COA3 and COA6 have been shown to generate an immune response in a murine sarcoma model and suggest potential for an immune cell attack on COA3 and COA6." (PMID 35159029, 2022).
cancer (2 papers, 2022 to 2024). A tumor composed of atypical neoplastic, often pleomorphic cells that invade other tissues. "Another interesting protein is the cytochrome c oxidase (COX) assembly factor COA3, which is involved in promoting a Warburg-like effect in cancer cells." (PMID 35805888, 2022). "Additionally, COX7B, IARS2, COA3 and NDUFA1 were associated with platinum resistance, cancer cell proliferation and invasion, highlighting their significance as potential therapeutic targets and prognostic biomarkers." (PMID 38534098, 2024).
infection (1 paper, 2022). The state of being infected such as from the introduction of a foreign agent such as serum, vaccine, antigenic substance or organism. "The converse was observed in the COA3 and COA6 PDXs, in which STAT1 expression decreased with M002 infection." (PMID 35159029, 2022).
COA3 also shares sentences with these, for which no sentence is quoted: cervical cancer (1 paper); encephalomyopathies (1); neurological disorders (1); tumor (1).